RN7SL698P (RNA, 7SL, cytoplasmic 698, pseudogene)
Gene: Miscellaneous RNA gene on chromosome 3 (128,785,147 to 128,785,448, forward strand). Ensembl gene ENSG00000244232.
Homologues: Orthologues: chimpanzee Metazoa_SRP (98% identical), macaque Metazoa_SRP (92% identical). Paralogues in human: RN7SL1 (79% identical), RN7SL2 (79% identical), RN7SL3 (79% identical), RN7SL118P (77% identical), RN7SL586P (77% identical), RN7SL19P (77% identical), RN7SL803P (77% identical), RN7SL20P (76% identical), RN7SL147P (76% identical), RN7SL665P (76% identical), RN7SL91P (76% identical), RN7SL122P (76% identical), and 703 more.